MGP (matrix Gla protein)
Diseases named in the same sentence as MGP in open-access papers (continued):
Sharing a sentence is not in itself a finding about the gene and the disease.
cardiovascular disease (20 papers, 2010 to 2025). "VK helps prevent calcium buildup in blood vessel walls by activating matrix Gla protein, potentially reducing the risk of cardiovascular disease and possibly counteracting pathogenic renal calcification." (PMID 39770962, 2024). "Multiple observational studies have since shown that low levels of inactive MGP, dephosphorylated–uncarboxylated MGP (dp-ucMGP), are associated with less vascular calcification and reduced cardiovascular disease (CVD) risk." (PMID 31387121, 2019). "In humans uncarboxylated MGP, which is an inactive form of MGP, is associated with the risk of cardiovascular disease and mortality." (PMID 31579595, 2019). "As MGP is expressed in kidney, lung and heart, in addition to bone and teeth, protein disfunction is associated with severe cardiovascular diseases." (PMID 28902892, 2017). "MGP is a vitamin K-dependent protein that helps prevent calcium from accumulating in the arterial walls and is associated with the signs of early vascular disease and the development of cardiovascular disease." (PMID 36615114, 2022). "MGP is the most powerful natural calcification inhibitor found in the human body, and is tightly associated with all types of calcification, mortality, and cardiovascular disease." (PMID 30717170, 2019). "Also, poor vascular vitamin K status, as concluded from high levels of circulating inactive MGP (Matrix Gla Protein), was found to be a risk factor for cardiovascular disease and mortality." (PMID 29617314, 2018). "Later studies showed that MGP serum levels in humans are influencing arterial calcification and cardiovascular disease, particularly in CKD patients in which they also associate with all-cause and cardiovascular mortality." (PMID 38186884, 2024). "Since then, a number of other studies have concentrated on SNPs in the MGP gene and their relationship to arterial calcification and cardiovascular diseases, some of them in CKD populations." (PMID 38186884, 2024). "In fact, a preventive role for vitamin K in cardiovascular disease has been proposed based on its action as an activator of matrix Gla protein, a calcification inhibitor that is also expressed in vascular tissue." (PMID 34322086, 2021). "Beyond coagulation, the role of VK in cardiovascular disease progression and mortality is increasingly recognized, particularly through its influence on extrahepatic VK-dependent proteins (matrix Gla protein [MGP], osteocalcin) and their impact on VC." (PMID 41300485, 2025). "We therefore speculate that vitamin K might be a potential link between COPD and cardiovascular disease by protecting against systemic elastin degradation through an MGP-dependent pathway." (PMID 36835797, 2023). "Conversely, studies have also demonstrated the potential utility of the non-functional MGP measurements to indicate vascular vitamin K status, cardiovascular disease risk and disease state, including calcification levels, in specific patient cohorts." (PMID 29584693, 2018). "The measurement of various species of non-functional MGP fractions may act as cardiovascular disease risk and disease markers correlating with future cardiovascular morbidity and mortality and also with the extent of prevalent vascular calcification." (PMID 29584693, 2018). "No or insufficient MGP activation by the use of VKAs is associated with a rapid progression of vascular calcification, which may enhance the risk for overt cardiovascular disease." (PMID 29132356, 2017). "While the role of VKA in calcification by way of the matrix Gla-protein pathway has been extensively studied, further mechanisms of VKA-induced cardiovascular disease remain to be elucidated." (PMID 34778390, 2021). "In contrast, endogenous calcium chelation with removal of calcium from the cardiovascular system paralleled by improved bone mineralization exerted, i.e., by matrix Gla protein (MGP) and osteocalcin, appears to significantly delay the development of cardiovascular diseases." (PMID 38137375, 2023).
renal disease (4 papers, 2020 to 2025). "Additionally, in children with auto-inflammatory conditions and children with kidney disorders a deficiency of vitamin K resulting in undercarboxylated non-functional matrix-gla protein (MGP) might contribute to the atherogenic process." (PMID 35053702, 2022). "Although MGP has been widely studied in the context of vascular and renal disease, no therapies specifically targeting MGP have been approved to date." (PMID 41303567, 2025).
infection (2 papers, 2023 to 2024). The state of being infected such as from the introduction of a foreign agent such as serum, vaccine, antigenic substance or organism. "The analysis also showed a specific pattern of MGP expression in EC 2 and EC-like myofibroblasts 1, 2, and 3 along the time course of infection, again supporting that MGP may regulate the transition from ECs to EC-like myofibroblasts." (PMID 37511258, 2023).
neurological disease (1 paper, 2020). "Finally, some studies reveal also that MGP could be implicated in neurological disease, as glioblastoma, and Alzheimer disease." (PMID 32092076, 2020). "As Matrix-gla-protein (MGP) is expressed in several components of the nervous system and is involved in some neurological disease, MGP could play a role in peripheral nervous system homeostasis." (PMID 32092076, 2020).
respiratory diseases (1 paper, 2025). "Recent studies have highlighted vitamin K as a possible factor in preventing cardiovascular and respiratory diseases by activating the vitamin K-dependent protein Matrix Gla Protein (MGP)." (PMID 40299372, 2025).
skeletal dysplasia (1 paper, 2023). Any Mendelian diseases that affects growth and development of the skeleton. "While KS is an autosomal recessive disorder, we suspected that the skeletal dysplasia described in this report was caused by heterozygous variants in MGP and followed an autosomal dominant mode of inheritance." (PMID 37923733, 2023). "Our work identifies potential cellular and molecular mechanisms underlying the skeletal dysplasia caused by heterozygous Cys19 variants in MGP." (PMID 37923733, 2023). "Future animal studies may provide insights on the yet unidentified pathways contributing to the skeletal traits caused by the C19F variant of MGP enabling further examination of various therapeutic approaches for this and other related skeletal dysplasias in humans." (PMID 37923733, 2023).
MGP also shares sentences with these, for which no sentence is quoted: Hypercalcemia (3 papers); metabolic disorder (3); aortic valve calcification (2); breast tumor (2); skin cancer (2); systemic sclerosis (2); triple-negative breast carcinoma (2); Acidosis (1); acute coronary syndrome (1); Alzheimer disease (1); aortic valve disease (1); basal cell carcinoma (1); brachydactyly (1); central neurocytoma (1); cerebrovascular disease (1); chondrosarcoma (1); Cirrhosis (1); cognitive decline (1); dementia with (1); diabetic kidney disease (1); end-stage renal disease (1); endocrine system disorder (1); gastric adenocarcinoma (1); genetic disorder (1); head and neck cancer (1); heart disease (1); hyperlipidemia (1); hyperparathyroidism (1); hyperuricemia (1); Hypocalcemia (1).
A further 28 diseases each share a sentence with MGP in 1 paper.